TRBJ1-6 (T cell receptor beta joining 1-6)
Description:
J region of the variable domain of T cell receptor (TR) beta chain that participates in the antigen recognition. Alpha-beta T cell receptors are antigen specific receptors which are essential to the immune response and are present on the cell surface of T lymphocytes. Recognize peptide-major histocompatibility (MH) (pMH) complexes that are displayed by antigen presenting cells (APC), a prerequisite for efficient T cell adaptive immunity against pathogens. Binding of alpha-beta TR to pMH complex initiates TR-CD3 clustering on the cell surface and intracellular activation of LCK that phosphorylates the ITAM motifs of CD3G, CD3D, CD3E and CD247 enabling the recruitment of ZAP70. In turn ZAP70 phosphorylates LAT, which recruits numerous signaling molecules to form the LAT signalosome. The LAT signalosome propagates signal branching to three major signaling pathways, the calcium, the mitogen-activated protein kinase (MAPK) kinase and the nuclear factor NF-kappa-B (NF-kB) pathways, leading to the mobilization of transcription factors that are critical for gene expression and essential for T cell growth and differentiation. The T cell repertoire is generated in the thymus, by V-(D)-J rearrangement. This repertoire is then shaped by intrathymic selection events to generate a peripheral T cell pool of self-MH restricted, non-autoaggressive T cells. Post-thymic interaction of alpha-beta TR with the pMH complexes shapes TR structural and functional avidity.
Synonyms: TRBJ16; TCRBJ1S6
Gene: T-cell receptor joining (J) gene on chromosome 7 (142,788,988 to 142,789,040, forward strand). Ensembl gene ENSG00000282780.
Subcellular location: Cell membrane
Gene Ontology:
Cellular component: plasma membrane